CHD4 (chromodomain helicase DNA binding protein 4)
Diseases named in the same sentence as CHD4 in open-access papers (continued):
Sharing a sentence is not in itself a finding about the gene and the disease.
Arrhythmia (2 papers, 2021 to 2022). Any cardiac rhythm other than the normal sinus rhythm. "Aberrant expression of skeletal muscle genes induced by the loss of Chd4 in the heart leads to sudden death due to defects in cardiomyocyte contraction that progress to arrhythmia and fibrosis." (PMID 36076959, 2022). "Four novel CHD4 mutations were identified in four unrelated families of childhood idiopathic epilepsy with sinus arrhythmia, suggesting that CHD4 was potentially a candidate causative gene of epilepsy with arrhythmia." (PMID 34109749, 2021). "CHD4 was potentially a candidate pathogenic gene of childhood idiopathic epilepsy with arrhythmia." (PMID 34109749, 2021). "Supporting this view, Znf219 knockdown in the adult heart induced the ectopic expression of some skeletal-muscle sarcomeric genes, which resulted in the induction of arrhythmias similar to those observed in Chd4 cKO mice." (PMID 36076959, 2022). "When Chd4 or Znf219 are removed from the cardiomyocyte, the skeletal muscle sarcomeric program is aberrantly expressed in the cardiomyocyte and this translates to the induction of arrhythmias, cardiac fibrosis, and, eventually, to heart failure." (PMID 36076959, 2022). "Identifying the transcription factors (TFs) that recruit Chd4/NuRD to repress skeletal muscle genes in the myocardium will provide important information for understanding numerous cardiac pathologies and, ultimately, pinpointing new therapeutic targets for arrhythmias and cardiomyopathies." (PMID 36076959, 2022).
carcinoma cervix (2 papers, 2021 to 2022). "CHD4 silencing in SiHa cervical carcinoma cells strongly diminished their colony forming capacity, potently increased PADI3 expression and stimulated glycolysis." (PMID 33741961, 2021).
congenital heart defects (2 papers, 2021 to 2026). "CHD4 mutations cause Sifrim–Hitz–Weiss syndrome, frequently associated with heart malformations as well as numerous other findings (Chiari malformation, Moyamoya disease, hypogonadism, deafness, and limb malformation)." (PMID 33944996, 2021).
epilepsy (2 papers, 2018 to 2021). A brain disorder characterized by episodes of abnormally increased neuronal discharge resulting in transient episodes of sensory or motor neurological dysfunction, or psychic dysfunction. "The results of clinical validity summary matrix were 12.3 points that was categorized as “Strong,” supporting the association between CHD4 variants and epilepsy." (PMID 34109749, 2021). "Strong evidence from ClinGen Clinical Validity Framework and evidences from four of the five clinical‐genetic aspects suggested an association between CHD4 variants and epilepsy." (PMID 34109749, 2021). "The Clinical Validity Framework of ClinGen and an evaluating method from five clinical‐genetic aspects were used to determine the association between CHD4 variants and epilepsy." (PMID 34109749, 2021). "We evaluated the CHD4 variant epilepsy correlation using ClinGen Clinical Validity Framework." (PMID 34109749, 2021). "CHD4 gene was considered as a candidate pathogenic gene of epilepsy." (PMID 34109749, 2021). "In the five clinical‐genetic dimensional evaluation, evidence from four of the five clinical‐genetic aspects (repetition, genotype‐phenotype correlation, inheritance pattern, and molecular sub‐regional implications) was ranked “Yes,” suggesting that epilepsy was a novel phenotype of CHD4 variants." (PMID 34109749, 2021). "However, the association between CHD4 mutations and epilepsy remains unknown." (PMID 34109749, 2021). "However, the role of CHD4 in epilepsy remains largely unknown." (PMID 34109749, 2021).
intellectual disability syndrome (2 papers, 2017 to 2020). "The structure thus suggests the effects of CHD4 mutations in cancer and intellectual disability syndromes on chromatin remodeling." (PMID 32543371, 2020). "De novo missense mutations in CHD4 are also associated with an intellectual disability syndrome with distinctive dysmorphisms." (PMID 32543371, 2020). "Mutations in CHD4 have also been implicated in intellectual disability syndromes." (PMID 32543371, 2020).
rhabdomyosarcoma (2 papers, 2020 to 2022). A rare aggressive malignant mesenchymal neoplasm arising from skeletal muscle. "The NuRD complex subunit CHD4 is essential for fusion-positive rhabdomyosarcoma (FP-RMS) survival, but the mechanisms underlying this dependency are not understood." (PMID 32744500, 2020). "Inhibition of BRG1 resolved differentiation blockade in fusion positive rhabdomyosarcoma cell lines, while depletion of CHD4, a coregulator of the oncogenic PAX3-FOXO1 transcription factor, resulted in reduced viability of fusion-positive but not of fusion-negative rhabdomyosarcoma in vitro." (PMID 36671446, 2022).
Snijders Blok-Campeau syndrome (2 papers, 2023 to 2025). Snijders Blok-Campeau syndrome (SNIBCPS) is an autosomal dominant neurodevelopmental disorder characterized by global developmental delay with impaired intellectual development and delayed speech acquisition. "Pathogenic variants in CHD proteins contribute to the development of a range of neurological disorders, such as CHD1 in Pilarowski-Bjornsson syndrome, CHD3 in Snijders Blok-Campeau syndrome (SNIBCPS), CHD4 in Sifram-Hitz-Weiss syndrome, CHD7 and CHD8 in Autism Spectrum Disorder (ASD)." (PMID 36647159, 2023).
thyroid cancer (2 papers, 2023 to 2024). "In thyroid cancer, deleterious variants of CHD4 were found to be restricted to metastatic lesions." (PMID 36681835, 2023).
uterine cancer (2 papers, 2018 to 2025). Primary or metastatic malignant neoplasm involving the uterine corpus and/or the cervix. "TGF β signaling promotes uterine cancer stemness and is known to be regulated by CHD4 mutation." (PMID 40004553, 2025). "Furthermore, two groups identified frequent somatic mutations in the NuRD component chromodomain helicase DNA-binding protein 4 (CHD4) in an aggressive form of uterine cancer." (PMID 29625565, 2018).
abdominal aortic aneurysm (1 paper, 2013). Enlargement and ballooning of the vessel that supplies arterial blood to the abdomen, pelvis and legs. "However, if CHD4 limits plasmin production in adult endothelium as it does in the embryo, it may play an important preventative role in vascular pathologies such as abdominal aortic aneurysms, which are associated with excessive ECM degradation around vessel walls." (PMID 24348274, 2013).
Alpha-thalassemia (1 paper, 2023). Alpha-thalassemia is an inherited hemoglobinopathy characterized by impaired synthesis of alpha-globin chains leading to a variable clinical picture depending on the number of affected alleles. "Moreover, chromatin remodelers, such as alpha thalassemia/mental retardation syndrome X-linked (ATRX) and chromodomain helicase DNA-binding protein 4 (CHD4), have been implicated in suppressing R-loops’ accumulation and promoting their resolution." (PMID 37894353, 2023).
atrial septal defect (1 paper, 2021). Interauricular communication is a congenital malformation characterized by a communication between the atrial chambers of the heart. "Previously, 65% of reported cases with CHD4 mutations had heart defects, including atrial septal defect, ventricula septal defect, pulmonary stenosis/anomaly, patent ductus arteriosus, tetralogy of fallot, mitral valve anomaly, ebstein anomaly, and truncus arteriosus." (PMID 34109749, 2021).
autoimmune disease (1 paper, 2022). A disorder resulting from loss of function or tissue destruction of an organ or multiple organs, arising from humoral or cellular immune responses of the individual to their own tissue constituents. "Most encouragingly, CHD4 is associated with both AS and DM activity, suggesting that it might be a potential biomarker during the autoimmune diseases process." (PMID 35759243, 2022). "Here, we reviewed the current knowledge of CHD4 and mainly focused on its function on lymphocytes differentiation and development as well as its role in autoimmune diseases." (PMID 35759243, 2022). "In conclusion, CHD4 provides us with a new insight into autoimmune diseases and is also a potential biomarker for disease diagnosis and an effective therapeutic target." (PMID 35759243, 2022). "In this review, we will discuss details of CHD4 in lymphocyte differentiation and development, as well as the critical role of CHD4 in the pathogenesis of the autoimmune disease." (PMID 35759243, 2022). "Emerging data indicated the relevance of CHD4 in T and B lymphocytes development and gene rearrangement that attributed to various cancers and several autoimmune diseases." (PMID 35759243, 2022). "In this review, we will discuss the details of CHD4 in lymphocyte differentiation and development, as well as the critical role of CHD4 in the pathogenesis of the autoimmune disease." (PMID 35759243, 2022). "In future studies, the relationship between CHD4 and Treg/Th17 may provide a new viewpoint for clinical diagnosis and disease surveillance of autoimmune diseases." (PMID 35759243, 2022). "Not least, CHD4 is closely related to DM, but there is a gap between CHD4 and other autoimmune diseases." (PMID 35759243, 2022).
Autoimmunity (1 paper, 2021). The occurrence of an immune reaction against the organism's own cells or tissues. "Chd4-deficient mice develop autoimmunity with T lymphoid infiltration of peripheral targets, including the salivary gland, kidney, lung, and liver." (PMID 33532929, 2021). "The discovery of other genes and pathways like Fezf2 and Chd4 that regulate mTEC development and TRA expression in murine models make it likely that other defects of intrathymic production of tTreg will be discovered in patients with autoimmunity or other forms of immune dysregulation." (PMID 33532929, 2021).
bladder carcinoma (1 paper, 2017). "Survival analysis showed that bladder carcinoma patients with mutations in CHD4 have better prognosis than patients with other mutated drivers." (PMID 29030609, 2017).
brain tumours (1 paper, 2019). "We show that CHD4 expression correlates with poor patient outcomes, and is a specific vulnerability in brain tumour cells." (PMID 30872624, 2019).
Burkitt lymphoma (1 paper, 2026). A rare form of malignant mature B-cell non-Hodgkin lymphoma. "We show that CHD4 and PRC1 components are novel repressors of BZLF1 gene expression and that both are required to prevent spontaneous lytic reactivation in Burkitt lymphoma cells." (PMID 41841741, 2026).
congenital heart disease (1 paper, 2023). A heart disease that is present at birth. "Research, both clinical and genetic, has linked the catalytic subunit of NuRD, Chromodomain helicase DNA-binding protein 4 (CHD4), with congenital heart disease (CHD), specifically atrial and ventricular septal abnormalities." (PMID 38124890, 2023).
diabetes (1 paper, 2025). "Together, our findings establish CHD3 and CHD4 as cooperative guardians of β-cell transcriptional programs and uncover a compensatory mechanism that transiently preserves β-cell resilience under metabolic stress but fails in diabetes progression." (PMID 41282155, 2025).
diffuse intrinsic pontine glioma (1 paper, 2023). A neuroglial tumor that arises from the middle portion of the brain stem. "A knockout screen on tumour sphere cells derived from diffuse intrinsic pontine glioma also ranked knockout of UBE2N, CHD4 and EED as a hit in combination with the histone deacetylase inhibitor panobinostat." (PMID 37161535, 2023).
epileptic syndromes (1 paper, 2021). "In this study, children with CHD4 mutations presented as CAE, BECTS, and EFS+, similar as several previously reported genes associated with idiopathic epilepsy, such as GABRG2, SCN9A, and GRIN2A,45, 46 suggesting these epileptic syndromes potentially have similar etiologies." (PMID 34109749, 2021).
Ewing sarcoma (1 paper, 2013). A small round cell tumor that lacks morphologic, immunohistochemical, and electron microscopic evidence of neuroectodermal differentiation. "We tested the necessity of these three co-repressors in BCL11B-mediated repression in Ewing sarcoma cells by shRNA knock-down for chomodomain helicase DNA binding protein 4 (CHD4), the core component of the NuRD complex, or chemical inhibitors targeting SUV39H1 or SIRT1." (PMID 23527175, 2013).
gynecological cancers (1 paper, 2021). "The present work shows that somatic mutations in CHD4 occur at low frequency in BC compared to other gynecological cancers." (PMID 33981601, 2021). "The present results confirm that CHD4 is also mutated in certain types of BC, but at a lower frequency than in other gynecological cancer (<3% of the BC tumors examined showed somatic mutations in CHD4)." (PMID 33981601, 2021).
head and neck cancer (1 paper, 2022). A primary or metastatic malignant neoplasm affecting the head and neck. "The biologic role of CHD4 in head and neck cancers remains elusive, but its identification as an oncogenic and cancer stem cell element associated with metastatic potential may implicate it as a novel therapeutic target for the treatment of various cancers." (PMID 36362284, 2022).
head and neck squamous cell carcinoma (1 paper, 2022). A squamous cell carcinoma that arises from any of the following anatomic sites: lip and oral cavity, nasal cavity, paranasal sinuses, pharynx, larynx, and salivary glands. "Given that HDAC inhibitors are currently being tested in clinical trials for head and neck squamous cell carcinomas and the demonstrated synergism when combined with EGFR inhibitors, CHD4 could constitute a clinically relevant response biomarker." (PMID 36362284, 2022).
hearing loss (1 paper, 2023). "Altogether, these findings on CHD4 mutations in hearing loss patients and the Chd4 pattern of expression in embryonic mice cochlea suggest that CHD4 may influence spatiotemporal gene expression regulation in the developing cochlea." (PMID 36831199, 2023).
Hydrocephalus (1 paper, 2021). Hydrocephalus is an active distension of the ventricular system of the brain resulting from inadequate passage of CSF from its point of production within the cerebral ventricles to its point of absorption into the systemic circulation. "This connection suggests a possible pathophysiological mechanism whereby lack of CHD4 activity may reduce NKCC1 levels during early development (equivalent to P0-P7 in mice), and lead to insufficient CSF clearance resulting in hydrocephalus." (PMID 33469018, 2021).
latent infection (1 paper, 2024). "Among the proteins localized in proximity to LANA, we showed that cellular CHD4 protein plays a key role in establishing and maintaining latent infection." (PMID 38240593, 2024).
lung squamous cell carcinoma (1 paper, 2022). "Compared with normal lung tissues, the expression of CHD4/6/7/8 in lung squamous cell carcinoma was higher, while the expression of CHD1/2, and to a less extent, was lower." (PMID 35467222, 2022).
lymph node metastasis (1 paper, 2019). "A high expression of CHD4 was significantly associated with pre-treatment tumor status (p < 0.001) and lymph node metastasis (p < 0.001), post-treatment tumor status (p < 0.001), and lymph node metastasis (p < 0.001), vascular invasion (p = 0.042), and tumor regression grade (p = 0.001)." (PMID 31438571, 2019).
microcephaly (1 paper, 2020). A congenital or acquired developmental disorder in which the circumference of the head is smaller than normal for the person's age and sex. "CHD4 likewise influences cortical development, and neuronal deletion of Chd4 with a Nestin-Cre results in lethality associated with microcephaly at birth." (PMID 32658897, 2020).
pancreatic cancer (1 paper, 2020). "In studies of pancreatic cancer, nuclear p-ERK staining levels were associated with poorer survival and this finding was in line with the correlation between CHD4 and survival observed in the current study." (PMID 32228507, 2020).
prostate carcinoma (1 paper, 2022). A carcinoma that arises from epithelial cells of the prostate gland. "Therefore, the importance of somatic mutation of CHD1 and germline mutation of CHD4 has been demonstrated in Chinese patients with prostate cancer compared to Western cohorts, highlighting the ethnic characteristics of CHD family genes in Chinese population." (PMID 36095024, 2022).
Rett syndrome (1 paper, 2023). A severe neurodevelopmental disorder affecting the central nervous system. "HDAC is already considered a potential target for Rett syndrome therapy; thus, there is great potential in systematically exploring the role of HDAC and CHD4 in developing novel therapies." (PMID 37408271, 2023).
schwannoma (1 paper, 2020). A benign, usually encapsulated slow growing tumor composed of Schwann cells. "Particularly, ATM, accounting for 33% of the samples, was the most frequently mutated cancer-related gene in schwannoma, followed by CHD4, FAT1, KMT2D, MED12, NF2, and SUFU (>20%)." (PMID 33193598, 2020). "Moreover, the different location of CHD4 staining has been reported to be used as a potential biomarker to differentiate cellular schwannoma from malignant peripheral sheath tumor (MPNST)." (PMID 33193598, 2020).
small cell lung carcinoma (1 paper, 2021). Small cell lung cancer (SCLC) is a highly aggressive malignant neoplasm, accounting for 10-15% of lung cancer cases, characterized byrapid growth, and early metastasis. "In addition, the ET domain–binding motif, which shares similar amino acid sequences from other BRD4-ET–binding proteins such as CHD4 and NSD2/3, also mediates interaction of BRD4-ET with ASXL3 and functionally links BRD4 to the BAP1 complex in a small-cell lung cancer (SCLC) subtype." (PMID 34540900, 2021).
tauopathies (1 paper, 2025). "Overall, RBPs enriched in disease-associated modules included the previously validated CHD4, MACROH2A1, SAFB, WDR82, and PAPOLA proteins, highlighting their potential relevance to tauopathies." (PMID 41205924, 2025).
thyroid tumor (1 paper, 2026). A benign or malignant neoplasm affecting the thyroid gland. "Furthermore, a high level of CHD4 is associated with the presence of capsular breach and vascular emboli, affirming the involvement of CHD4 in thyroid tumor aggressiveness." (PMID 41908702, 2026).
type 1 diabetes (1 paper, 2025). "Whether interactions between CHD3, CHD4 with PDX1 are compromised in other β-cell stress conditions, for example, during type 1 diabetes progression, remains to be established." (PMID 41282155, 2025).
uterine carcinosarcoma (1 paper, 2022). A usually aggressive malignant neoplasm arising from the uterine corpus and less often the cervix.
vascular malformation (1 paper, 2023). A non-neoplastic disorder that is the result of defects of vascular morphogenesis. "This includes some of the genes for moyamoya phenomenon, other vascular malformations, abnormalities of coagulation including CBL, DIAPH1, CHD4, CNOT3, and SETD5." (PMID 36253534, 2023).
virus infection (1 paper, 2022). "High concurrency of CHD4 and H3K27ac in the virus-induced-TE regions may suggest functional dependency between CHD4 and H3K27ac, where CHD4 reduces chromatin accessibility and suppresses transcription events to maintain poised enhancer status prior to virus infection." (PMID 35140280, 2022).